SOD2 (superoxide dismutase 2)
Diseases named in the same sentence as SOD2 in open-access papers (continued):
Sharing a sentence is not in itself a finding about the gene and the disease.
autism (continued). "Furthermore, in vivo rat experiments showed that maternal diabetes induces SOD2 suppression in the amygdala, resulting in autism-like behavior in offspring." (PMID 31685635, 2019). "RSV-mediated ERβ activation then upregulates the expression of SOD2 and ERRα and minimizes the oxidative stress and dysfunction of mitochondria and lipid metabolism, subsequently ameliorating prenatal progestin exposure-induced autism-like behavior." (PMID 30123446, 2018). "Furthermore, maternal diabetes induces SOD2 suppression in offspring with autism-like behavior." (PMID 31685635, 2019). "ERβ suppression results in decreased expression of SOD2 and ERRα, and subsequently triggers damage in amygdala tissue through oxidative stress and the dysfunction of mitochondria and fatty acid metabolism, and eventually contributes to autism-like behavior in offspring." (PMID 28824796, 2017). "As additional evidence regarding these observations, the levels of superoxide dismutase 2 (SOD2), one of the chief antioxidant enzymes, are lowered in children with autism, while those of hydrogen peroxide were seen to be raised." (PMID 37284987, 2024). "We hypothesize that HSCT with increased Sod2 expression diminishes maternal diabetes–mediated systematic oxidative stress and epigenetic changes in neurons, subsequently ameliorating ALB in autism‐like offspring." (PMID 35220596, 2022). "Furthermore, suppression of ERβ and its target genes, including SOD2 and ERRα, results in oxidative stress and dysfunction of mitochondria and fatty acid metabolism, which may directly or indirectly contribute to tissue damage and the subsequent autism-like behavior development." (PMID 28824796, 2017).
lymphoma (13 papers, 2007 to 2025). A malignant (clonal) proliferation of B- lymphocytes or T- lymphocytes which involves the lymph nodes, bone marrow and/or extranodal sites. "Mice heterozygous for a null allele of Sod2 also exhibit increased levels of oxidative damage to DNA and form tumors, particularly lymphoma and pituitary adenoma." (PMID 37898799, 2023). "Moreover, the life-long reduction of SOD2 activity results in increased DNA damage and a significantly higher incidence of lymphoma." (PMID 35667246, 2022). "The main finding of this study is that by reproducing in vitro a condition of in vivo hyperCHO, lymphoma lymphoblastic cells overexpressed genes for antioxidant proteins (SOD1, SOD2, CCS, GSR, GSS and CAT) with the only exception of GRX2." (PMID 26754536, 2016).
pulmonary fibrosis (13 papers, 2018 to 2026). Chronic progressive interstitial lung disorder characterized by the replacement of the lung tissue by connective tissue, leading to progressive dyspnea, respiratory failure, or right heart failure. "Previous studies unveiled that the expression and activity of SOD2, one of the main antioxidant enzymes, was reduced during pulmonary fibrosis." (PMID 37815883, 2023). "NAMPT deficiency impaired AT2 renewal and enhanced lung fibrosis through downregulation of SIRT7 and SOD2, which resulted in increased oxidative stress, mitochondrial dysfunction, accumulated aberrant transitional cells, and impaired differentiation from AT2 to alveolar type 1 (AT1) cells." (PMID 42096291, 2026). "Notably, the deacetylation of SOD2 is predicted to be a major mechanism through which SIRT3 reduces mitochondrial DNA damage and apoptosis in lung fibrosis." (PMID 41502422, 2025). "Significantly attenuated vascular remodeling and increased pulmonary SOD2 expression without measurable effects on pulmonary fibrosis." (PMID 34746028, 2021). "Acute treatment with ACE2 significantly attenuated vascular remodeling and increased pulmonary SOD2 expression without measurable effects on pulmonary fibrosis." (PMID 29731719, 2018).
viral infection (13 papers, 2016 to 2025). "Post PCV2 infection, we identified 199 differentially expressed lncRNAs, which appear to modify genes associated with viral infection, such as SOD2, TNFAIP3, ARG1, SERPINB2, VLDLR, HSPA5, and LCN2." (PMID 30863688, 2019). "To summarize, HDH ameliorates the antioxidant system induced by viral infection by activating the antioxidant proteins Sirt3 and SOD2." (PMID 39857405, 2025). "Several target genes are notably connected to immune or antiviral functions; for example, SOD2 (targeted by dro-miR-1302; binding energy −17.9 kcal/mol) plays a well-established role in countering oxidative stress during viral infection." (PMID 41227394, 2025). "However, overexpression of either human VHL(Δ61+R161W) mutant or BW-VHL via lenti-virus infection in 780-O cells under hypoxia enhanced expression of PAI-1and SOD2 significantly." (PMID 28178687, 2017). "However, SOD2, which is mainly located in the mitochondria, significantly increased upon viral infection." (PMID 26761025, 2016). "Here, we showed that OLE and OA reduced the transcription of SOD2, which was upregulated upon Poly(I:C)-stimulation as an NF-kB responsive gene, highlighting the contribution of these compounds in restoring the impaired redox homeostasis in the context of acute viral infections." (PMID 37627504, 2023). "Here, we found that the virus infection significantly decreased the protein levels of both SOD2 and CAT at the late stage of infection (16 h after infection), which may compromise their capacity of converting O2−· into H2O2 in the mitochondrial matrix as well as detoxifying H2O2 in the cytosol." (PMID 31011285, 2019). "For instance, overexpression of SOD2 could be protective from ROS-mediated cell damage, but it may also increase the invasiveness of tumors and achieve higher possibility of infection, while SOD2 suppression may inhibit virus infection due to the over-generation of ROS." (PMID 28977893, 2017). "The decreased protein levels of both SOD2 and CAT due to virus infection indicated a decreased capability to counteract ROS production, which is in agreement with the finding that the virus infection stimulated ROS overproduction." (PMID 31011285, 2019). "The expression of antioxidant enzymes including superoxide dismutase 1 (SOD1), SOD2, catalase (CAT), and glutathione peroxidase 4 (GPX4) was differentially affected following the virus infection." (PMID 31011285, 2019). "In addition, we found that virus infection broadly affected the expression of the antioxidant enzymes such as SOD1, CAT, GPX4, and SOD2 at both mRNA and protein levels." (PMID 31011285, 2019). "Overexpression of human wild-type VHL via lenti-virus infection in 780-O cells under hypoxia had no obviously effect on expression of PAI-1 and SOD2, two well-defined HIF-2α down-stream genes." (PMID 28178687, 2017).
epilepsy (12 papers, 2014 to 2025). A brain disorder characterized by episodes of abnormally increased neuronal discharge resulting in transient episodes of sensory or motor neurological dysfunction, or psychic dysfunction. "Furthermore, the observed associations between rs1137101 (LEPR) and rs4480 variants (SOD2) with weight gain and hair loss further highlight the importance of personalized medicine in managing epilepsy." (PMID 39539630, 2024). "Further, the forebrain neuron-specific conditional knockout of SOD2 also leads to the presentation of epilepsy in mice." (PMID 36035987, 2022). "In conclusion, this study demonstrated that the SOD2 Val16Ala polymorphism has an impact on the relationship between VPA exposure and γ-GT elevation in patients with epilepsy, as determined using a population PK-PD modeling approach." (PMID 25372290, 2014). "Our results showed that the SOD2 Val16Ala polymorphism has an impact on the relationship between VPA exposure and γ-GT elevation in patients with epilepsy." (PMID 25372290, 2014). "Astrogliosis is prevalent in the epilepsies, and interestingly a mouse forebrain neuron-specific knockout of SOD2 resulted in seizures, oxidative stress, and marked GFAP and vimentin gene upregulation, indicative of astrogliosis resulting from increased neuronal mtROS." (PMID 36035987, 2022). "During the model developments, we evaluated the associations of the VPA-induced γ-GT elevation with patient-specific covariates, including the SOD2, GSTM1 and GSTT1 genotypes, in Japanese patients with epilepsy." (PMID 25372290, 2014). "Since patients with epilepsy usually receive long-term VPA from childhood, our results suggest that VPA-treated patients should be carefully monitored for γ-GT elevation, especially those with the SOD2 Val/Val genotype." (PMID 25372290, 2014). "Pertinent to epilepsy, mice lacking mitochondrial SOD (Sod2−/−) and heterozygous animals (Sod2+/−) show higher seizure susceptibility and concomitant degeneration, introducing the notion that O2− are key players in the long-term brain changes after a seizure episode." (PMID 35052661, 2022).
ischemic stroke (12 papers, 2018 to 2025). A stroke disorder caused by obstruction of blood flow to the brain, due to thrombotic (local blood clot formation) or embolic (due to a blood clot or other material traveling from another site) event. "SOD2 gene polymorphism was significantly associated with the prognosis of ischemic stroke." (PMID 40235548, 2025). "We have demonstrated that SIRT3 protects the brain from ischemic stroke by modulating superoxide dismutase 2 (SOD2) and the forkhead box O3a (FoxO3a)." (PMID 31208274, 2019). "Thus, to confirm the functional importance of Nrf2 activation in Ginseng’ neuroprotection, Nrf2 downstream target markers including NQO1, HO1, SOD2 and GPx in peri-infarct tissue of cortex were measured at earlier-stage of ischemic stroke onset." (PMID 29628876, 2018). "Meanwhile, we found that Ginseng pretreatment significantly enhanced expression levels of Nrf2 downstream cytoprotective and antioxidative proteins including NQO1, HO1, SOD2 and GPx1 at the early stage of ischemic stroke onset in WT, and this was completely abolished in the Nrf2−/− mice." (PMID 29628876, 2018). "Interestingly, without effects on NSC proliferation, IFN-γ elevated the superoxide dismutase 2 (SOD2) level in NSC culturing, which improved the therapeutic effects of NSCs in the ischemic stroke model." (PMID 36552117, 2022).
multiple myeloma (12 papers, 2007 to 2025). "For instance, epigenetic silencing of SOD2 in KAS 6/1 human multiple myeloma cells can increase cell proliferation." (PMID 34777635, 2021). "The SOD2 promoter has been shown to have a higher frequency of methylation in a number of cancer cell lines including multiple myeloma, breast and pancreatic cell lines with low SOD2 expression." (PMID 29099803, 2017). "More recently, reduced expression of SOD2 has been seen in multiple myeloma cells, androgen-independent prostate cancer, and invasive breast carcinoma." (PMID 17895890, 2007). "Indeed, high IL-6 has been shown to favor SOD2 expression in prostate, myeloma and brain cells affording protection against interventions inducing a cellular oxidative stress." (PMID 32365668, 2020). "More recently, we have found that the sod2 promoter is methylated in some multiple myeloma cells and diminished expression can be reversed by the methyltransferase inhibitor zebularine, suggesting that repression of SOD2 may occur at the level of epigenetic regulation." (PMID 17895890, 2007).
sarcopenia (12 papers, 2015 to 2025). Progressive decline in muscle mass due to aging which results in decreased functional capacity of muscles. "They ultimately identified five candidate causal proteins associated with sarcopenia, including LILRB2, ASPN, CNTN2, ART4 and SOD2." (PMID 39949133, 2025). "In a previous paper, we showed that nitration of protein tyrosine residues, as well as SOD-1 and SOD-2 expression, are both increased in the skeletal muscle of aged mice, and many authors also reported increased oxidative stress levels in sarcopenia." (PMID 41009681, 2025). "We investigated the putatively potential causal effects of genetically predicted plasma protein levels on sarcopenia-related traits and identified three putatively causal proteins for ALM (LILRB2, ASPN, and CNTN2) and two for handgrip strength (ART4 and SOD2)." (PMID 35938019, 2022). "Compared with the control group, the expression level of SOD2 in the HF + sarcopenia group was significantly decreased (P < 0.05)." (PMID 35126176, 2021). "Nitration of protein tyrosine residues (3-NT), as well as SOD1 and SOD2 (expression were both increased in skeletal muscle from aged mice, consistent with increased oxidative stress in sarcopenia." (PMID 26485763, 2015).
type 1 diabetes (12 papers, 2012 to 2025). "The association between rs4880 at SOD2 gene and DPN in type 1 diabetes in the European population was regarded as highly credible under the allelic model (C vs. T), dominant model (CC+CT vs. TT), and recessive model (CC vs CT+TT)." (PMID 40116328, 2025). "Eight SNPs in the SOD2 region were analysed in 1285 Caucasian subjects with type 1 diabetes from the SURGENE prospective study (n = 340; 10-year follow-up), GENESIS (n = 501) and GENEDIAB (n = 444) cross-sectional studies." (PMID 24819633, 2014). "Interruption of glucose supply with reduced PPP and NADPH generation, such as during a hypoglycaemic event in type 1 diabetes (where induction of Sod2 and Hmox-1 is impaired), will further hamper detoxification of ROS and the induction of antioxidant defence proteins." (PMID 37015997, 2023). "Interestingly, further western blot data and immunohistochemistry staining showed that type 1 diabetes markedly down-regulated myocardial AMPK phosphorylation level and the expressions of PGC-1α, SIRT3 and SOD2." (PMID 28120943, 2017).
diabetic cardiomyopathy (11 papers, 2011 to 2025). Diabetic cardiomyopathy is a disorder of the heart muscle in people with diabetes. "Sirt3, a mitochondrial deacetylase, is known to preserve mitochondrial function and suppress necroptosis in diabetic cardiomyopathy and reduce ROS via activation of SOD2 in cardiac I/R injury." (PMID 40635895, 2025). "During diabetic cardiomyopathy, SOD2 can protect cardiac morphology and ultimately normalize cardiomyocyte contractility." (PMID 40462170, 2025). "Stem cell transplantation restores Sirt-1 and SOD2 expression, resulting in ROS/inflammasome signaling blocking and diabetic cardiomyopathy improvement." (PMID 36354780, 2022). "In addition to blocking GP91, we find that antioxidant proteins, as well as Sirt-1 and SOD2 expression, also play an important role in ameliorating diabetic cardiomyopathy progression through scavenging ROS production." (PMID 36354780, 2022). "Similarly, increased SOD2 expression has been shown to be protective against ischemia reperfusion injury, xenobiotic cardiotoxicity, alcohol-induced liver injury, and diabetic cardiomyopathy." (PMID 21169125, 2011).
injury (11 papers, 2011 to 2025). Damage inflicted on the body as the direct or indirect result of an external force, with or without disruption of structural continuity. "In a rat model of myocardial ischemia/reperfusion (I/R) injury, the cardioprotective effect of the acacetin prodrug was partially attributed to its ability to prevent the reduction of antioxidant proteins superoxide dismutase 2 (SOD2) and thioredoxin." (PMID 40255574, 2025). "In the case of the SOD2+/− animals, a strong increase was observed in SOD2+/− animals subjected to brain trauma." (PMID 34679709, 2021). "Regarding the 2-month-old SOD2+/− used as control of the transgenic animals, we observed a decline in the total response compared to the WT control animals and an even stronger decrease in SOD2+/− mice subjected to brain trauma." (PMID 34679709, 2021). "On the other hand, the phospho-tyrosine 1336 labels of the animals SOD2+/− control has relative levels similar to the WT animals, but the SOD2+/− animals subjected to brain trauma present an increase of this phosphorylation close to 60%." (PMID 34679709, 2021). "In the case of SOD2+/− animals, the reversal of damage induced by brain trauma after treatment with TC-2153 is even more evident." (PMID 34679709, 2021). "As we have found a decrease in the response corresponding to NMDARs, we decided to analyze changes in the distribution of NMDARs between synaptic and extrasynaptic regions that could contribute to the neuropathological effects observed after brain trauma in WT and SOD2+/− mice." (PMID 34679709, 2021). "ROS removal is regulated by many antioxidant enzymes, including SOD1, SOD2, GPX, and catalase, and overexpression of SOD2 protects against alcohol-induced liver injury." (PMID 24069053, 2013). "Retinal transfection of AAV-expressing CAT and superoxide dismutases 2 (SOD2) prolonged cone photoreceptor survival in mice during retinal degeneration, and AAV-CAT also exerts neuroprotective effects on retinal ganglion cells in ischemia-induced retinal injury in rats." (PMID 36187472, 2022). "To evaluate the effect of accumulation of oxidative stress on synaptic transmission after brain trauma, we have recorded synaptic activity in the collateral hippocampal circuit of Schaffer-CA1, measuring excitatory postsynaptic field evoked potentials (fEPSP) in WT and SOD2+/− mice." (PMID 34679709, 2021).
Nephropathy (11 papers, 2014 to 2023). A nonspecific term referring to disease or damage of the kidneys. "A meta-analysis found that rs4880 showed a significant correlation between nephropathy in both T1DM and T2DM, suggesting that the C allele of a C47T polymorphism in the SOD2 gene had significant protective effects on the risk of DN." (PMID 30719346, 2019). "ML171 reduced H2O2 in the IRI mouse, and the effect was manifested as a subsequent increase in SOD2 and GPX in MDCK cells, suggesting the prevention of kidney damage with oxidative stress by selective NOX1 inhibition." (PMID 32967113, 2020). "Our findings suggested that Nrf2 plays an important role in the regulation of the Sirt3/SOD2 antioxidative pathway, and t-BHQ may be a potential agent to ameliorate radiocontrast-induced nephropathy via activating the Nrf2/Sirt3/SOD2 signaling pathway in vitro and in vivo." (PMID 31929854, 2019). "The role of NOX4, but not TRX2 and SIRT3/SOD2 signaling pathway, in UUO and IRI-induced nephropathy has been reported." (PMID 35355864, 2022).
breast tumor (10 papers, 2004 to 2025). "Cancer cells are known to have elevated ROS regulated by the SODs, and SOD2 plays a role in activating different signaling pathways, regulating the angiogenic abilities of breast tumor cells." (PMID 40426890, 2025). "SOD2 plays a role in cell proliferation and cell invasion via activation of different signaling pathways regulating angiogenic abilities of breast tumor cells." (PMID 35164076, 2022). "We have discussed these lines of evidence and proposed a model of the signaling pathways linking CD44 activation by HA to the transactivation of SOD2 to promote breast tumor cell invasion." (PMID 35164076, 2022). "Oroxylin A, a flavonoid extracted from a Chinese medicinal plant, can induce SOD2 gene expression, glycolysis inhibition, and reduced tumor growth of transplanted human breast tumors in vivo." (PMID 35164076, 2022). "Furthermore, we observed a significant increase in the expression of GSTM1 and SOD2, two key enzymes related to ROS detoxification, in the basal-like breast tumours of overweight/obese patients compared to those of lean patients." (PMID 34073320, 2021). "SOD2, iNOS, MMP2, MMP9 were evaluated through western blot and TUNEL test preformed for breast tumor." (PMID 39503169, 2024). "However, the scavenging system used by BCSCs to protect from radiation is most likely not restricted to SOD2/MnSOD and may vary between samples from different patients and even within the different cells of a breast tumor." (PMID 22479642, 2012).